INS (insulin)
Diseases named in the same sentence as INS in open-access papers (continued):
Sharing a sentence is not in itself a finding about the gene and the disease.
diabetes (continued). "Selective radical overgeneration in adipose tissue may possess a prominent role in insulin resistance development, diabetes, and CVD through impairment of muscle glucose uptake and secretion of insulin from β cells." (PMID 30564116, 2018). "The frequency of diabetes, the prescription of oral hypoglycemic agents and the use of insulin were not different in progressors and non-progressors." (PMID 30209259, 2018). "Other significant independent correlates with higher diabetes burden in people with diabetes included self-reported insulin use, self-reported frequent non-severe hypoglycemia and self-reported severe hypoglycemia." (PMID 29347915, 2018). "This protective effect is also observed in vivo, e.g., GABA treatment prevents insulitis and diabetes onset and preserves insulin expression in NOD mice and in multiple low-dose STZ-induced diabetes in C57BL/6 mice and delays hyperglycemia in the adoptive transfer of disease in NODscid mice." (PMID 29867762, 2018). "The transition to insulin does not affect this relationship, suggesting hypoglycaemia in itself has a detrimental effect on diabetes-related QoL independent of treatment regimen." (PMID 28803366, 2018). "Diabetes is commonly treated with medications such as insulin secretagogues and sensitizers (e.g. biguanides and thiazolidinediones (TZD)) which engage the proximal insulin signaling." (PMID 30521580, 2018). "For older glucose-lowering agents, such as insulin and sulfonylureas, there is insufficient evidence indicating the effects on HF outcomes in patients with diabetes and with established HF due to the lack of randomized controlled trials." (PMID 30343339, 2018). "As hypoglycemia often represents a barrier to optimization of diabetes therapy, this result means that persons with T2DM receiving basal insulin analogues may be able to make better use of the benefits of insulin-based treatment." (PMID 29460260, 2018). "The material features of SkypeTM enabled the development of ‘ad hoc’ consulting in the young adult diabetes clinic, for example, when the patient saw that the clinician was online and sent a text (SMS) message asking a question about a recently changed insulin dosage." (PMID 29754584, 2018). "Moreover, in this study, men with prediabetes and DM showed similar fasting insulin levels." (PMID 30185190, 2018). "Interestingly, NYT contains atractylodes rhizome, ginseng, and glycyrrhiza, which are components of Ninjin-to preventing the progression of diabetes, Furthermore, NYT also contains astragalus root, which improves insulin resistance." (PMID 30538991, 2018). "Taken together, the results of the study suggest that OA improves insulin sensitivity in diet-induced pre-diabetes even in the absence of diet intervention." (PMID 29596390, 2018). "The mean LH concentrations did not change after intranasal insulin in healthy lean men or in men with diabetes." (PMID 30515210, 2018). "Advice, particularly on managing insulin doses and carbohydrate intake around exercise, needs to be available both to HCPs and patients with T1DM so that we can help patients to develop confidence managing their diabetes both generally and around exercise." (PMID 29371269, 2018). "In our clinical experience, many patients are not sure of their diabetes type and, in the absence of blood tests (i.e., insulin autoantibodies, c-peptide), providers cannot always be entirely certain of diabetes type among patients treated only with insulin." (PMID 30400859, 2018). "Though the exact number of patients using Insulin in Sri Lanka is not known, the rapid rise in the number of patients living with diabetes in the country is most likely to have increased this number exponentially." (PMID 30555274, 2018). "The first involves insulin deprivation, which occurs in STZ-induced diabetes." (PMID 29795129, 2018).
diabetes (continued). "Unlike most species, horses rarely develop diabetes mellitus, but instead retain good pancreatic capacity for insulin secretion in response to excessive oral carbohydrates." (PMID 29958298, 2018). "There are four main categories: pre-diabetes (a stage prior to diabetes), type 1 (where the pancreas fails to produce insulin), type 2 (the body fails to use insulin), and gestational diabetes (which occurs during pregnancy)." (PMID 30360409, 2018). "Typically, most insulin-resistant subjects are able to increase their β-cell secretory capacity to meet the increased insulin demand and therefore, do not develop diabetes." (PMID 29649104, 2018). "Despite 92% of physicians agreeing that “insulin intensification is an essential element of diabetes management,” 30% of primary care physicians “never or rarely” personally intensified insulin (vs 4% of specialists) in the multinational survey MODIFY." (PMID 29476414, 2018). "This type of diabetes was described in the 1960s in patients who maintain glycemic control without insulin therapy after an episode of DKA." (PMID 30526658, 2018). "Diabetes is a chronic disorder that occurs either when the pancreas is no longer able to produce insulin (type 1 diabetes, T1D), or if body tissues and organs cannot effectively utilize circulating insulin (type 2 diabetes, T2D)." (PMID 29534053, 2018). "Significant differences were found in statin use, NSAID use, systolic blood pressure (SBP), diastolic blood pressure (DBP), TG, fasting plasma glucose, fasting insulin, HOMA-IR, duration of diabetes, HbA1c, eGFR and urinary ACR between the diabetic patients and the control subjects (all P < 0.05)." (PMID 30072957, 2018). "Therefore, the BC-mediated insulin sensitivity is partly owed to the increased Nrf2 and the decreased PARP-1 to alleviate diabetes-induced oxidative stress and inflammation." (PMID 30072896, 2018). "Diabetes mellitus (DM) is defined as a chronic disease that occurs either when the pancreas fails to produce sufficient insulin which is type 1 diabetes or when the body cannot effectively use the produced insulin which is called type 2 diabetes." (PMID 30068392, 2018). "In the early years of its discovery, insulin therapy, although capable of saving lives for people with diabetes, was not able to protect them from the development of diabetic complications." (PMID 30274207, 2018). "Following lifestyle and diet changes, patients usually start with oral antidiabetic drugs (OADs), then as their diabetes advances, a glucagon-like peptide-1 receptor agonist (GLP-1RA) and/or a basal insulin may be introduced as required." (PMID 30226870, 2018). "A similar decrease in diabetes incidence was observed in female NOD mice treated with BL001 from week 12, an age at which these animals feature an ongoing autoimmune attack, and reduced insulin content." (PMID 29662071, 2018). "Participants in the 3 latent classes were similar in age, race, education, marital status, SF-12, CES-D, Diabetes Care Profile (results not shown), chronic diseases, BMI, A1c, use of insulin, 6 MW, gait speed, and peak VO2." (PMID 29662686, 2018). "Together, these results suggest that prior exposure to insulin-induced hypoglycemia in the diabetic disease state is associated with elevated GAM, but that diabetes itself is not sufficient to increase GAM." (PMID 29931424, 2018). "Conversely, it has been demonstrated in a mouse model which does not produce insulin, that when insulin levels were low, such as occurs in later stage diabetes, IDE expression was significantly decreased." (PMID 30387070, 2018). "The aim of the present study was to investigate if a 16-week pioglitazone (PIO) therapy can improve first phase insulin secretion and insulin resistance in newly diagnosed non-obese type 2 diabetes patients in comparison with obese diabetes patients." (PMID 29536426, 2018).
diabetes (continued). "In addition, TUDCA reduced the incidence of diabetes and insulitis in NOD mice as well as improved insulin secretion and beta cell morphology." (PMID 30386256, 2018). "The lack of reliable data on insulin use in the region necessitates the need for high-quality studies to be carried out in East Africa; they will help in making treatment decisions in diabetes management." (PMID 29508275, 2018). "Compared with age-matched individuals without diabetes, a gradual increase in absolute dense volume was found with duration of insulin treatment in T1D patients." (PMID 30092829, 2018). "There are two types of diabetes mellitus: Type 1 is the lack of insulin due to a destructive process in pancreatic β-cells and Type 2 is a steady decline in the use of glucose due to resistance of the tissues to insulin." (PMID 29671829, 2018). "In diabetes, this protein misfolding implicates the islet amyloid polypeptide protein (IAPP, also known as amylin), which is a short peptide that is packaged and secreted along with insulin from pancreatic beta cells." (PMID 30622456, 2018). "For previously diagnosed diabetes participants, the relationship of insulin and HOMA-IR levels with age was not significant after multivariate adjustment." (PMID 30211231, 2018). "Conversion of the insulin dosing guide to a smartphone app might improve utilization of the protocol and further increase the use of BBI for inpatient diabetes management by internal medicine house staff." (PMID 30155381, 2018). "Among them, mutations in hepatocyte nuclear factors HNF4α, HNF1α, HNF1β, insulin promoter factor IPF1, and NeuroD genes may induce different hereditary forms of diabetes mellitus such as the maturity onset diabetes of the young (MODY)." (PMID 30002646, 2018). "Our data show that one dose of 40 IU of regular insulin administered intranasally does not change LH concentrations acutely in healthy lean men or in men with diabetes." (PMID 30515210, 2018). "Like other studies, we found a dramatic improvement in insulin sensitivity by surgical treatment, and most of our patients had no signs of diabetes post surgery, especially those on diet control preoperatively." (PMID 30220006, 2018). "In the current study, fasting plasma glucose levels, fasting insulin levels and HbA1c values did not increase markedly over the 26 weeks of the trial, and no cases of diabetes were diagnosed." (PMID 29500310, 2018). "In children and young adults with diabetes, who are typically non-obese and rapidly insulin dependent, both genetically defined type 1 diabetes and islet-antibody-positive diabetes define almost all patients." (PMID 29199115, 2018). "This was performed in a 36-year-old woman with type 1 diabetes mellitus, who received transplantation of approximately 800,000 islet equivalents and who subsequently achieved normoglycemia for 22 days without insulin treatment." (PMID 29735923, 2018). "The investigators found that longer-term remission (after 2 to 4-years follow-up) was more likely in patients not using insulin with less than 2-year duration of diabetes, a lower baseline HbA1c, and a greater first-year weight loss." (PMID 30061841, 2018). "When the synthesis of insulin by β cell or sensitivity of cells to insulin is impaired, it leads to hyperglycaemic condition along with other complications such as uricosuria, ketoacidosis and negative nitrogen balance, collectively called as diabetes mellitus (DM)." (PMID 29337286, 2018). "For instance, despite experiencing high or low glucose values, some informants deemed their diabetes to be controlled because insulin injections were not a component of their treatment regime." (PMID 30214920, 2018). "Compared with age-matched individuals without diabetes, insulin-treated T2D patients had greater percent dense (7.8% vs. 6.5%) and absolute dense (58.0 vs. 52.6 cm3) volumes, as well as a smaller absolute nondense volume (754 vs. 679 cm3)." (PMID 30092829, 2018).
diabetes (continued). "So was more active drug ingredients and having previously treated RxMG conditions such as allergy/immunology/chronic inflammatory, general signs and symptoms/pain and inflammation, diabetes without insulin, and cardiovascular/high blood pressure." (PMID 29720237, 2018). "In this study, we examined the effects of liraglutide versus metformin on non-esterified free fatty acids, beta-cell insulin secretion, and adhesion molecule levels in patients with recent-onset type 2 diabetes mellitus." (PMID 29636047, 2018). "Compared to the non-DKD patients, those with DKD were older with a prolonged duration of diabetes, higher prevalence of hypertension, higher ARB or ACEI medication, higher use of insulin, higher WHtR, SBP, DBP, HbA1c, FPG, TG and lower Hemoglobin (HGB) (all P < 0.05)." (PMID 29549262, 2018). "At least one episode of hypoglycaemia was recorded for 27/79 (34%) insulin-treated patients, compared to 4/85 (5%) sulphonylurea-treated patients, 2/121 (2%) metformin-only treated patients, and none in patients without diabetes." (PMID 28918198, 2018). "Irrespective of diabetes control, the greatest visit‐to‐visit variability was observed in young, insulin resistant men." (PMID 28755478, 2018). "Because PI4KIIα regulation of PKD and insulin secretion is independent of kinase activity, it is hard to evaluate its therapeutic effect in animal models of diabetes using inhibitors." (PMID 29577067, 2018). "Maternal blood glucose and plasma insulin values and fetal latencies of auditory event-related brain responses for the two subgroups with a negative family history of diabetes (FHD–, n = 37) and a positive family history of diabetes (FHD+, n = 15)." (PMID 30524370, 2018). "The management of patients with diabetes in noncritical care settings is based on basal-bolus insulin protocols according to contemporary guidelines." (PMID 30373567, 2018). "The decline or absence of insulin release has dire metabolic consequences, including severe hyperglycemia and diabetes." (PMID 30098928, 2018). "In the diabetes model, WEL reduced the BGL and enhanced the plasma insulin and body weight." (PMID 35542112, 2018). "Pen needles are an important component of insulin delivery among patients with diabetes, but are not universally covered in China." (PMID 29699587, 2018). "There were no clear changes in incident unclassified diabetes and in those using non-insulin glucose-lowering medication without having a registered diabetes diagnosis." (PMID 29995214, 2018). "However, when insulin was co-administered, the serum CA125 curve resumed its peak times and peak levels in all four cancer xenograft diabetes animal models." (PMID 29716620, 2018). "In people that do not have diabetes, plasma insulin falls with exercise duration and/or intensity due to exercise-induced catecholamine inhibition on pancreatic ß-cell function." (PMID 29342932, 2018). "In summary, administration of the SIRT1 activator, SRT3025, to mice with STZ-induced diabetes led to improved glycaemia with reductions in plasma glucagon and α cell hyperplasia without affecting either insulin secretion or ß-cell mass." (PMID 30228292, 2018). "Diabetes results from either impaired insulin production in the pancreas or body cells not responding to produced insulin." (PMID 29467962, 2018). "CRP, insulin and HOMAIR were all significantly elevated in patients with diabetes." (PMID 29975702, 2018). "Diabetes mellitus is one of the most refractory metabolic disorders characterized by increased blood glucose level, as a result of an absolute or relative lack of insulin and failure of insulin to act on targets tissue." (PMID 29862294, 2018). "There was no change in LH concentrations following insulin administration as compared to placebo in men with diabetes or in lean men." (PMID 30515210, 2018).
diabetes (continued). "In the absence of a cure, insulin replacement is mandatory for survival in patients with type 1 diabetes mellitus and requires them to be thoroughly informed and trained." (PMID 29529063, 2018). "First, although differentiation protocols lead to hPSC-derived beta-like cells that have the capacity to cure diabetes in immunodeficient mice, these cells do not have the same “mature” insulin secretory capacity as primary human beta cells." (PMID 30250968, 2018). "Diabetes was insulin-dependent and not ketosis onset, with antibody to glutamic acid decarboxylase and islet cell negative." (PMID 29483894, 2018). "After LSG, 37% did not receive any medication for diabetes, 21% had their doses reduced, 11% had their doses increased and/or had to take insulin, and 32% did not notice any change in their treatment." (PMID 28707172, 2018). "For many, diabetes control incorporated the prescription of oral medication only, whereas necessity of insulin injections represented a lack of disease control." (PMID 30214920, 2018). "There were 10 predicting features identified for this study: systolic blood pressure (SBP), diastolic blood pressure (DPB), body mass index (BMI), age, gender, duration of disease, family history of diabetes, self-monitoring blood glucose (SMBG), exercise, and insulin treatment." (PMID 30367589, 2018). "Nevertheless, the pathologic role of brain insulin in hippocampus in diabetes-related depression is not fully explained." (PMID 30622594, 2018). "Conversely, SIRT4 and SIRT7 exhibited negative effect on diabetes therapy, such as aggravating lipogenesis, and inhibiting insulin secretion." (PMID 30559718, 2018). "In addition, type 1 diabetes mellitus (T1DM) is also characterized by a proinflammatory state and by requiring insulin exogenous treatment." (PMID 29850590, 2018). "To study whether genetic hyperactivation of autophagy exerts beneficial effects on diabetes, we treated the mice with an HFD for 8 weeks and performed glucose tolerance tests (GTTs) and insulin tolerance tests (ITTs)." (PMID 29898399, 2018). "In people without diabetes, the first response to a decline in blood glucose is a reduction in insulin secretion that begins while plasma glucose concentration is still in the physiological range (~4.4 mmol/l)." (PMID 29417183, 2018). "In this mammography screening cohort, we found that insulin-treated T1D and T2D patients had higher MD levels as compared with age-matched individuals without diabetes and diabetes patients receiving other noninsulin glucose-lowering medication." (PMID 30092829, 2018). "In people without diabetes, developing hypoglycaemia leads to the suppression of endogenous insulin secretion (insulin ‘switch-off’) and a parallel rise in glucagon release from the pancreatic alpha cell." (PMID 29417183, 2018). "on the other hand, no conclusive treatment has been found for diabetes, while taking oral drugs and insulin injection are among common treatments." (PMID 30595825, 2018). "Although men are more likely to have diabetes (13.6% males vs 11.2% females have diabetes), they are very unlikely to have an interest in Insulin index." (PMID 29592849, 2018). "The remaining 2 had significantly longer durations of diabetes (26 and 30 years), therefore, it was considered by the clinician that a change of therapy would not be appropriate, so they continued receiving insulin treatment." (PMID 29666556, 2018). "A significantly higher percentage of patients with diabetes who were treated with glucocorticoids during hospitalization did not achieve glycemic control with a basal-bolus insulin protocol." (PMID 30373567, 2018). "Treatment with a selective HDAC3 inhibitor also reduces hyperglycemia and increases insulin secretion in type-2 diabetes in mice, which indicates that HDAC3 may be a potential target for the therapy of diabetes." (PMID 29498635, 2018).